INS (insulin)
Diseases named in the same sentence as INS in open-access papers (continued):
Sharing a sentence is not in itself a finding about the gene and the disease.
type 2 diabetes (continued). "No change in the achieved insulin concentration or the C‐peptide response was detected during infusion of 50 mU∙m−2 min−1 in the individuals with type 2 diabetes, following MR blockade compared to before MR blockade." (PMID 34350730, 2021). "Although predominantly used for the treatment of type 1 diabetes, insulin is also now commonly used for the treatment of type 2 diabetes if lifestyle changes and oral medication do not help to sufficiently control glucose levels." (PMID 33807829, 2021). "Given the high insulin levels that accompany disorders such as adult-onset type 2 diabetes, future work should also seek to determine whether insulin, either through IR or IGF1R, or insulin resistance modulates adult oligodendrogenesis using in vivo models." (PMID 33672939, 2021). "In type 2 diabetes patients, PR and RI were significantly higher in patients receiving long-term insulin treatment than in those without (P < 0.01)." (PMID 34283877, 2021). "Within 5 years, 36% of people with type 2 diabetes did not improve their insulin sensitivity despite increasing PA levels." (PMID 34659107, 2021). "Results from a proteomic study assessed IRS-1 protein interactions in skeletal muscles from normal individuals, obese insulin-resistant nondiabetic control subjects, and patients with type 2 diabetes, before and after insulin infusion." (PMID 34183055, 2021). "On the other hand people with type 2 diabetes do not always have to inject insulin, but cope more often with multi-morbidity and multi-pharmacy." (PMID 36994341, 2021). "Conversely, another meta-analysis of seven trials reported that consumption of green tea did not affect fasting plasma glucose and insulin levels, post-load plasma glucose, glycated hemoglobin, and HOMA-index in subjects at risk of new-onset type 2 diabetes." (PMID 33923263, 2021). "The effect of insulin treatment on liver fat content and liver enzymes in individuals with uncontrolled type 2 diabetes and NAFLD has not been extensively studied and no prospective trial has examined its effect on liver histology." (PMID 33877366, 2021). "Patients over 30 years of age diagnosed with type 2 diabetes who did not require insulin for a minimum of 6 months following diagnosis were included." (PMID 34033299, 2021). "In patients with type 2 diabetes who have not had prior MACE or who have stable coronary heart disease, insulin use is associated with elevated risk of incident or recurrent MACE and death despite use of evidence-based cardiovascular therapies." (PMID 34158057, 2021). "Another study showed that taking 2 g/day of black seeds for 3 months decreased FBG, 2-h post-prandial glucose (2-hPG), HbA1c, and increased insulin sensitivity without any renal or hepatic side effects in individuals with type 2 diabetes mellitus." (PMID 35011050, 2021). "As the widely used drugs for the treatment of patients with type 2 diabetes, SUs could bind specifically to the SUR1 subunit, then closing the KATP channel via an ATP-independent mechanism and therefore increasing the insulin secretion of β cells." (PMID 34631896, 2021). "In patients with insulin‐treated type 2 diabetes, CONGA1, CONGA2, and CONGA4 were not affected by combining resistance and interval aerobic exercise performed at 12:00." (PMID 33904659, 2021). "In Pima Indians with normal glucose tolerance, evidence was found that fasting hyperinsulinemia itself, independent of a low rate of insulin-stimulated glucose uptake, predicted the cumulative incidence of type 2 diabetes during a 7 year follow-up." (PMID 34360563, 2021).
type 2 diabetes (continued). "The IMPACT and REPLACE studies conducted with the FreeStyle Libre 1 sensor in adults with T1D or type 2 diabetes (T2D) on insulin therapy showed no decrease in HbA1c compared to SMBG." (PMID 34768429, 2021). "However, in obese individuals with type 2 diabetes, excessive IMCL is negatively correlated with compromised plasma fatty acids, which induces insulin resistance in skeletal muscle." (PMID 34508782, 2021). "Glycogen synthase kinase-3 (GSK-3), which phosphorylates and inactivates glycogen synthase, is elevated in insulin resistant states including individuals with type 2 diabetes independent of obesity and in animal models." (PMID 34943997, 2021). "A short-term experimental study of healthy individuals with and without a family history of type 2 diabetes who were overfed by 5200 kJ/day for 28 days, showed that those with a family history of type 2 diabetes had greater insulin resistance by the end." (PMID 34442147, 2021). "We reported an eight times increased frequency of insulin-positive cells co-expressing glucagon and a five times increased frequency of NKX6.1-positive, insulin-negative cells co-expressing glucagon in donors with type 2 diabetes compared to the control group." (PMID 34804002, 2021). "The molecular docking analysis data of beta-caryophyllene with the insulin downstream signaling molecules such as IRS-1 cSrc and Akt reveals its ability and further studies are needed to elucidate its complete mechanism of action against type-2 diabetes." (PMID 35655910, 2021). "Therefore, it is of interest to document the molecular docking analysis data of Beta-Caryophyllene with the downstream insulin signaling molecules such as IRS-1, cSrcand Akt for the management of type-2 diabetes." (PMID 35655910, 2021). "Decades later, development of radioimmunoassay confirmed that insulin concentrations are high, not low, in many people with type 2 diabetes (Yalow and Berson, 1960a,b)." (PMID 34841432, 2021). "Fruit extracts of M. charantia showed a slight hypoglycemic effect on nine type 2 diabetic patients without a significant change in insulin levels." (PMID 34885816, 2021). "2D and 3D cocultures were differentiated in the presence or absence of high insulin levels and high glucose levels to simulate the development of a type 2 diabetes." (PMID 33805833, 2021). "One week after RYGB, enhanced insulin sensitivity and fasting hepatic insulin clearance was shown in 10 subjects with obesity and with or without type 2 diabetes." (PMID 34959892, 2021). "In type 2 diabetes, there is generally enough insulin but the cells upon which it should act are not normally sensitive to its action." (PMID 34912774, 2021). "In type 2 diabetes, hepatic gluconeogenesis is higher than normal in the post-absorptive state and fails to be properly suppressed by insulin, resulting in excessive glucose production rather than glycogenolysis." (PMID 33669133, 2021). "Among patients with type 2 diabetes and ACS, approximately 35% receive chronic insulin treatment." (PMID 34158057, 2021). "Incretins are intestinal hormones that regulate insulin production in response to oral intake of nutrients, called the ‘incretin effect’, which is lacked in patients with type 2 diabetes." (PMID 33687487, 2021). "For example, adults with type 2 diabetes who do not use insulin and adults from ethnic minority groups were underrepresented." (PMID 36994341, 2021). "The treatment showed no beneficial effect on insulin sensitivity in individuals with type 2 diabetes." (PMID 34350730, 2021). "In another study, glucose-stimulated insulin secretion was not affected by the intake of chlorella (C. vulgaris), while it improved insulin sensitivity in type 2 diabetic Goto-Kakizaki (insulin resistant with impaired β-cell function) and normal Wistar rats." (PMID 33572056, 2021).
type 2 diabetes (continued). "Characteristics of type 2 diabetes patients treated in primary care using only oral antihyperglycemic agents or using insulin with or without oral antihyperglycemic agents." (PMID 33776906, 2021). "Therefore, it is of interest to document the molecular dockinganalysis data of beta-Caryophyllene, a naturally occurring sequiterpene with the downstream insulin signaling molecules such as IRS-1, cSrc and Akt for the management of type-2 diabetes." (PMID 35655910, 2021). "A study utilising face-face interviews examined the prevalence of primary non-adherence with insulin and barriers to insulin initiation in patients with type 2 diabetes." (PMID 34111207, 2021). "In INSTRIDE 2, patients with type 2 diabetes treated with oral antidiabetic drugs, insulin naive or not, received MYL-1501D or reference insulin glargine over a 24-week period." (PMID 34174848, 2021). "Type 2 diabetes mellitus (T2DM) is a complicated endocrine and metabolic disease, in which chronic hyperglycemia is provoked by peripheral insulin resistance and impaired release of insulin." (PMID 33833872, 2021). "Collectively, no beneficial effect of MR blockade on insulin sensitivity was detected in individuals with type 2 diabetes compared to healthy controls." (PMID 34350730, 2021). "We previously reported lower insulin-stimulated oxidative and nonoxidative glucose disposal in obese youth with type 2 diabetes compared with nondiabetic controls of similar adiposity." (PMID 33616083, 2021). "No change in insulin sensitivity was detected at the end of the mineralocorticoid blockade in the individuals with type 2 diabetes or the healthy controls." (PMID 34350730, 2021). "It is not clear if youth with type 2 diabetes or early dysglycemia have a defect in metabolic flexibility compared with insulin-resistant youth with obesity but with normoglycemia." (PMID 33616083, 2021). "IR in type 2 diabetes is only partially compensated, with insulin concentration high, but not high enough to normalise blood glucose." (PMID 34841432, 2021). "When dysfunctional pancreatic islet cells can not compensate for defective insulin secretion, it will develop to overt type 2 diabetes." (PMID 34352018, 2021). "Globally, one in two people with type-2 diabetes have no access to the insulin they need; however, in some LMICs, this proportion is only one in six to seven patients have access to insulin." (PMID 34645430, 2021). "In humans, vitamin D supplementation improves insulin secretion in response to oral glucose in patients with mild or early type II diabetes, prediabetes, and healthy subjects, but not in well-established full-blown diabetes." (PMID 34070202, 2021). "In type 1 diabetes (T1D) or in late stages of type 2 diabetes (T2D), the insulin-producing beta cell mass is dramatically decreased, resulting in a lack of insulin." (PMID 33445518, 2021). "Transplantation of pancreatic islets has potential to offer life-long blood glucose management in type I diabetes and severe type II diabetes without the need of exogenous insulin administration." (PMID 33737913, 2021). "One study concluded that, based on drug therapy, long-term supplementation with an adequate amount of dietary fiber can restore the insulin sensitivity in some patients with type 2 diabetes to the normal levels, thus correcting the glucose metabolism." (PMID 34276373, 2021). "In type 2 diabetes, however, insulin action fails to suppress gluconeogenesis, yet it keeps activating lipogenesis, pairing two deadly weapons of metabolic syndrome: “hyperglycemia” and “hyperlipidemia”." (PMID 34319011, 2021). "All patients were type 2 diabetes patients with a mean HbA1c of 8.5 ± 1.9% (excluding 75 without HbA1c measurement), and 218 of them were insulin users." (PMID 33472648, 2021).
type 2 diabetes (continued). "We have interpreted that the suppression of the hepatic insulin clearance by Zn2+ ions results in the reach of enough insulin to the whole body via blood circulation, leading to type 2 diabetes therapy without insulin injection." (PMID 34959365, 2021). "Our objective was to determine the linearity of the relationship between fasting C-peptide (CPR) as a marker of endogenous insulin secretion and GV in type 2 diabetes (T2DM), regardless of the type of antidiabetic treatment." (PMID 33907279, 2021). "In patients with type 2 diabetes, DNA methylation of the insulin promoter was increased as compare with non-diabetic donors, and correlated negatively with insulin gene expression in human pancreatic islets." (PMID 34136553, 2021). "Here the authors show that a mild cold acclimation regiment during which overt shivering was prevented did not result in improved insulin sensitivity in a small group of patients with type 2 diabetes." (PMID 33750795, 2021). "According to the American Diabetes Association (ADA) recommendations, the use of CGMS is advocating for children and youths with T1D but, so far, no recommendations have been settled for type 2 diabetes people without insulin therapy." (PMID 34566883, 2021). "Data were also limited in individuals with type 2 diabetes for insulin iAUC and not available for insulin iPeak and thus, more studies would be useful to improve the precision of our findings in this population." (PMID 33608654, 2021). "Specifically, people with type 1 diabetes experience more immediate risks of ketoacidosis when not administering insulin, whereas the direct consequences are less dire when people with type 2 diabetes miss multiple doses of glucose lowering tablets." (PMID 36994341, 2021). "Type 1 diabetes is characterized by a lack of insulin production, while Type 2 diabetes is characterized by ineffective use of insulin in the body, which causes the blood glucose concentration to increase." (PMID 33562762, 2021). "Similar results were found with a swertisin rich flavonoid fraction both in insulin resistance hepatic cells and in high fat diet (HFD)-fed and streptozotocin (STZ)-induced type 2 diabetic rats, as well as with the flavonoid tangeretin in (db/db) diabetic mice." (PMID 34208379, 2021). "Our results suggest that 8 weeks of MR blockade, does not have a beneficial effect on insulin sensitivity in individuals with type 2 diabetes compared to healthy controls." (PMID 34350730, 2021). "Although the hypoglycaemia rate was not high in adults with type 2 diabetes treated with insulin, there was a lower percentage of patients that achieved glycaemic target among those reporting hypoglycaemia events versus patients who did not report them." (PMID 33532606, 2021). "Administration of polysaccharides triggers insulin signaling pathways through insulin receptors, and activates the PI3K/Akt pathway by elevating the expressions of the insulin receptor (IRS1), PI3K, and Akt in type 2 diabetic animal models." (PMID 33467194, 2021). "Type 2 diabetes mellitus (T2DM) is a progressive chronic disease that is marked by the inability of tissues such as the liver and skeletal muscles to respond to insulin, it has become a significant global healthcare problem and its reported incidence is increasing at an alarming rate." (PMID 34260520, 2021). "Additionally, mitochondria activate reactive oxygen species (ROS) production in a type 2 diabetes (T2D) diet-induced obesity (DIO) model, indicating a significant role for mitochondrial dysfunction in glucose homeostasis and insulin resistance." (PMID 34879063, 2021). "On the contrary, the flavonoid myricetin up-regulated p-IR, p-IRS1 and p-AKT in the liver of HFD-fed and STZ-induced type 2 diabetic rats by inhibiting the activity and expression of PTP1B, the tyrosine phosphatase that negatively regulates the insulin signal transduction." (PMID 34208379, 2021).
type 2 diabetes (continued). "For the 60 million people with type 2 diabetes who need insulin treatment, 1 in 2 of them do not get insulin due to its price." (PMID 34336550, 2021). "No beneficial effect of MR blockade was detected on insulin sensitivity in the individuals with type 2 diabetes compared to healthy controls." (PMID 34350730, 2021). "Among patients with type 2 diabetes, those treated with insulin were more likely to be screened than those who were not." (PMID 33594476, 2021). "This indicates that the cells might maintain secretory competence and may explain the restoration of insulin secretion by sulfonylureas and glucagon-like peptide 1 (GLP-1) based treatments in type 2 diabetic patients." (PMID 33399909, 2021). "One study showed that acute normalisation of fasting glucose concentrations in individuals with type 2 diabetes with variable insulin infusion for 67 h decreased EGP without changing peripheral insulin resistance but increased hepatic triacylglycerol content." (PMID 33877366, 2021). "Hepatic TG accumulation is inversely correlated with whole-body insulin clearance during the hyperinsulinemic clamp in lean and obese individuals with and without type 2 diabetes." (PMID 33498493, 2021). "Insulin resistance (IR) can be defined as a condition in which peripheral tissues do not respond sufficiently to insulin, which gradually leads to impaired glucose tolerance and later to the development of type 2 diabetes." (PMID 33494341, 2021). "Insulin concentrations were not measured, since the available assay would not detect concentrations of some long-acting insulin analogs in the patients with type 2 diabetes, which would complicate interpretation of data." (PMID 34085953, 2021). "Impairment of beta cell function is integral to the pathogenesis of type 2 diabetes, but most patients nevertheless do not require insulin treatment to control blood glucose." (PMID 34912295, 2021). "Patient reported outcomes of type 2 diabetes patients using only oral antihyperglycemic agents or using insulin with or without oral antihyperglycemic agents." (PMID 33776906, 2021). "Only 11% of the participants with known type 2 diabetes were treated with diet, 83% was treated with oral glucose-lowering agents, with or without insulin, while 6% was using insulin alone." (PMID 33435948, 2021). "This is particularly relevant for people with newly diagnosed type 2 diabetes, who exhibit a rise in HCL during the early course of disease, likely resulting from enlarging adipose tissue volume and insulin resistance in the face of impaired hepatic mitochondrial adaptation." (PMID 33839905, 2021). "In the present study, we used CGM to investigate whether endogenous insulin secretion, evaluated using fasting CPR, has a log-linear relationship with GV in type 2 diabetes, including those with severely impaired endogenous insulin secretion." (PMID 33907279, 2021). "In particular, due to lack of insulin in the body, insulin treatment is absolutely necessary for type 1 diabetes, whereas type 2 diabetes patients can control blood sugar through diet or exercise, so self‐management is especially important for them." (PMID 34482664, 2021). "Men and women (aged ≥ 50 years) with established or newly detected type 2 diabetes whose HbA1c level was 9.5% or less on stable doses of up to two oral glucose­ lowering drugs with or without basal insulin therapy were eligible for randomization." (PMID 33397395, 2021). "In type 2 diabetes, the metformin action consists mostly of decreasing glycemia without increasing plasma insulin concentrations." (PMID 34884872, 2021). "The combination of insulin and IGF-1 resistance in skeletal muscle in mice, due to expression of a mIGF-1R (mouse IGF-1 receptor), which forms nonfunctioning hybrids with native IR (insulin receptor) and IGF-1Rs (IGF-1 receptors), leads to type 2 diabetes." (PMID 34420367, 2021).